GNAQ (G protein subunit alpha q)
Diseases named in the same sentence as GNAQ in open-access papers (continued):
Sharing a sentence is not in itself a finding about the gene and the disease.
tumor (continued). "In this mutation sequence, the BAP1 mutation has been assumed to occur relatively late in tumor progression, preceded by oncogenic mutations in G-protein subunits including GNA11 and GNAQ that are present in as high as 83–96% of UM7." (PMID 33903674, 2021). "In examining five key mutations in UM (GNAQ, GNA11, BAP1, SF3B1 and EIF1AX), the xenograft tumours matched the genomic signature of the original patient tumours in 83% of cases." (PMID 34149931, 2021). "These mutations are typically found in GNAQ and GNA11 wild-type tumours and provide an alternative way to activate the Gαq signalling pathway." (PMID 35006486, 2021). "Genetic analysis of tumor tissue was performed using a diagnostic biochip (EIMB RAS, Russia) for the detection of most common somatic mutations in the BRAF, NRAS, KIT, GNAQ, GNA11, MAP2K1, and MAP2K2 genes." (PMID 30782194, 2019). "Genetic analysis of the tumor was performed using a diagnostic biochip for the detection of somatic mutations in the BRAF, NRAS, KIT, GNAQ, GNA11, MAP2K1, and MAP2K2 genes, Sanger sequencing for searching germinal mutations in the CDKN2A gene." (PMID 30782194, 2019). "In contrast to the dogma that GNAQ/11 mutation leads directly to MAPK activation and tumor survival, there is a subset of GNAQ/11 mutated UM tumors which lack significant MAPK activity." (PMID 31173078, 2019). "Most UMs harbor one Gq pathway mutation (GNAQ, GNA11, CYSLTR2, or PLCB4), one BSE mutation (BAP1, SF3B1, or EIF1AX), and a few recurrent CNAs, in 100% of tumor cells." (PMID 29317634, 2018). "Considering the hallmark driver mutations in the GNAQ and GNA11 paralogs were observed in 100% of cases, a model of tumor evolution based on genetic mutational events progressively occurring in all the four tumor subgroups is provided." (PMID 29156643, 2017). "Recurrent mutations in GNAQ and GNA11 initiate UM development while tumour progression is correlated with monosomy of chromosome 3 and gain of chromosome 8q." (PMID 25764247, 2015). "In our previous study, whole–exome sequencing of 127 NKTCL patients revealed that 8.7% harboured somatic mutations in GNAQ, specifically the T96S mutation in the Gαq protein, and GNAQ T96S mutations were associated with advanced tumour stage and inferior clinical outcomes in NKTCL." (PMID 41362935, 2025). "Nonetheless, while GNAQ mutations have been reported in KHE, their exact contribution to tumor development remains unclear, and it is still debated whether they represent a primary driver or a secondary event." (PMID 41303262, 2025). "GNAQ suppresses NKTCL tumour growth by inhibiting the AKT and MAPK signalling pathways." (PMID 41362935, 2025). "Gene set enrichment analysis (GSEA) of our transcriptome sequencing results revealed that the RHOA signalling pathway may contribute to the tumour–suppressive function of GNAQ." (PMID 41362935, 2025). "In a clinical setting where tumor tissue is unavailable, comprehensive screening for all oncogenic mutations in both paralog genes GNAQ and GNA11 as well as in CYSLTR2 and PLCB4, would be necessary to improve the detection rate of tumor-derived DNA in ocular fluids." (PMID 40461505, 2025). "Tumor-intrinsic P2RY6 has been shown to activate the GNAQ/GNA11–PLCB pathway." (PMID 41383622, 2025). "Although the predictive value of mutations in G-protein genes GNA11 and GNAQ in patients with primary CNA melanocytic neoplasms remains unknown, a lot of studies are held to find out if this feature might be useful for tumor diagnostics." (PMID 39518110, 2024). "However, the oncogenic or tumor-suppressive roles of GNAQ in cancer development remain controversial." (PMID 37240145, 2023). "It has also been questioned whether the type and location of mutation in the GNAQ and GNA11 genes may affect the progression of these tumours." (PMID 35804836, 2022).
tumor (continued). "The authors concluded that the univariate analysis of patients with tumours harbouring mutations in GNAQ or GNA11 genes was not significantly lower than in wild-type tumours." (PMID 35804836, 2022). "Nevertheless, even in the absence of statistically significant results, several investigations have suggested a more aggressive course of tumours with the mutated GNA11 gene, due to the general observation of a trend towards longer survival among patients with tumours carrying GNAQ mutations." (PMID 35804836, 2022). "By contrasts, tumor entities that contribute to the second and third main clusters, which is predominated by alterations resulting in GNAQ or GNA11 p.Q209 (indicated by grey bars), mostly show later age at diagnosis and therefore are presumably initiated during adulthood." (PMID 31336681, 2019). "No tumor presented concomitant variants in GNAQ/GNA11 and in SF3B1 or BAP1." (PMID 34359736, 2021). "During our investigation of the function of GNAQ in promoting NKTCL, we unexpectedly identified the tumour–suppressor gene RHOA as a potential player." (PMID 41362935, 2025). "While this study focuses on the cell–intrinsic functions of the GNAQ/RHOA axis in NKTCL cells, the impact of RHOA signalling within the tumour microenvironment (TME) remains to be elucidated." (PMID 41362935, 2025). "Genes enriched in GNAQ-UM and BRAF-CM were identified by those with a Log2FC > 1 and Adj p-value < 0.0001 between the two tumor types." (PMID 40950146, 2025). "UM is characterised by genetic mutations to the paralogous guanine nucleotide-binding protein Gq subunits alpha and alpha-11 (GNAQ and GNA11, respectively) which are observed in 80–90% of tumours." (PMID 38398064, 2024). "In our cohort, we have found in AH a significantly higher concentration of GNAQ protein in the UM group compared to the control group, therefore its overexpression in AH may reflect the hyperactive state of the protein in the tumoral tissue, which is essential for activating the tumor growth." (PMID 38175637, 2024). "Since the initial UM sequencing studies, there has been controversy about the possible involvement of the GNAQ and GNA11 genes in the prognosis of these tumours." (PMID 35804836, 2022). "In particular, studies on UM have identified aqueous and vitreous humor as sources of circulating tumor DNA, but no studies have been specifically conducted on GNAQ, BAP1, SF3B1, and EIF1AX related proteins." (PMID 38175637, 2024). "Among them, ERBB4 and NPM1 are presumably involved in cSCC tumorigenesis; in addition, GNAQ, GNAS, JAK2, NRAS, IDH2, and CTNNB1 may be related to tumor metastasis." (PMID 36780540, 2023). "Tumor DNA from a cohort of 100 UM patients from Moorfields Biobank (UK) that had undergone enucleation were sequenced for known UM driver genes (BAP1, SF3B1, EIF1AX, GNAQ, and GNA11)." (PMID 36077643, 2022). "The limitation of this report is lacking additional genetic analysis such as looking for GNAQ, GNA11, NRAS mutations, or tumor mutation burden." (PMID 33327228, 2020). "Additionally, GNAQ, GNAS, JAK2, NRAS, IDH2, and CTNNB1 are cancer-related genes that may be related to tumor metastasis." (PMID 36780540, 2023). "Strong correlations were noted between mutations in oncogenes and tumor suppressor genes and non-T cell-inflamed tumors with examples including IDH1 and GNAQ as well as less well-known genes including KDM6A, CD11c, and genes with unknown functions." (PMID 33106165, 2020). "We electroporated these DCs either without RNA (mock) or with a panel of 16 different RNAs encoding tumor antigens, or parts thereof (MelanA, NRAS, BRAF, GNAQ, GNA11, and WT1), either mutated or not, and either linked to the lysosomal targeting signal DC-LAMP or not." (PMID 26824052, 2015).
cancer (93 papers, 2013 to 2026). A tumor composed of atypical neoplastic, often pleomorphic cells that invade other tissues. "Mutations in GNAQ can result in the activation of these signaling pathways, promoting uncontrolled cell growth and survival as key features of cancer cells." (PMID 40151649, 2024). "The biological term enrichment analysis of the mRNAs of this subnetwork revealed pathways associated with cancer, such as the enrichment of the GNAQ, STAT1 and AKT3 oncogenes in the MAPK signaling pathway." (PMID 38302900, 2024). "Another alteration caused by GNA11 and GNAQ mutations concerns the calcium signaling pathway, whose dysregulation has a well-documented association with cancer survival, proliferation, migration, and metastatic potential." (PMID 36765733, 2023). "The spontaneous malignant transformation was characterized by a near-total whole-genome doubling, disappearance of NF2 mutation and new mutations in three cancer-related genes (GNAQ, FOXO4 and PDGFRB)." (PMID 34816314, 2022). "Cancer genome sequencing efforts have identified frequently mutated genes in UM, including GNAQ, GNA11, BAP1, SF3B1, and EIF1AX7,25." (PMID 32277165, 2020). "The majority of upregulated proteins have been previously linked to tumorigenesis or cancer homeostasis, including signaling molecules (integrin αV, GNAQ, GNA11, the latter two being associated with UM tumorigenesis), molecular chaperon (HSPB1), and an ESCRT-I complex subunit (i.e., TSG101)." (PMID 33050649, 2020). "Cancer genome sequencing studies using UVM have identified frequent mutations in GNAQ/GNA112." (PMID 31848373, 2019). "Recent investigations have highlighted the role of Gαq subunits encoded by GNAQ, GNA11, GNA14, and GNA15 in cancer development." (PMID 37760541, 2023). "In conclusion, these genetic findings highlight the importance of understanding the roles of BRAF, ARID2, KMT2C, and GNAQ in different cancer types, shedding light on potential therapeutic targets and predictive markers for cancer treatment strategies." (PMID 38023196, 2023). "Of these genes, GNAQ, GNAS, and JAK2 are associated with cell growth-related factors, whereas NRAS, IDH2, and CTNNB1 are cancer-related genes." (PMID 36780540, 2023). "For instance, alterations in the CTNNB1 and APC genes can lead to activation of the Wnt signaling pathway, whereas activating GNAQ mutations can lead to Hippo-independent activation of YAP pathways and cancer progression." (PMID 36497457, 2022). "It seems that VS1, already exhibiting genomic instability, undergoes a near whole-genome doubling as well as acquires new mutations in cancer-related genes (FOXO4, GNAQ, PDGFRB), thereby completing the malignant transformation." (PMID 34816314, 2022). "The GNAQ oncogene is the major oncogenic driver for UM, a cancer type characterized by limited additional genetic aberrancies." (PMID 36596361, 2022). "MEK inhibitors have been proven to be effective in cancers with constitutive activation of the MAPK/ERK pathway and have been investigated in UM, which displays GNAQ/GNA11-mutations in >90% of cases." (PMID 34201614, 2021). "Of 87 patients, 21 patients were analyzed by NGS with 48 selected cancer genes including GNA11, GNAQ and FBXW7, and 66 patients were analyzed for mutations by NGS with 592 cancer genes including BAP1 and SF3B1 mutations as well as MYC amplification." (PMID 34830903, 2021). "The development of specific inhibitors for GNAQ, efficacy of which was shown in vitro and in vivo, has paved the road for a rational therapeutic approach in cancers carrying alterations in this particular protein." (PMID 32532044, 2020). "We also detected another five smRMGs that mutated in nearly half of the samples in corresponding cancers, including PCDHAC2 in SKCM (53%), ZFPM1 in ACC (52%), VHL in KIRC (49%), GNAQ in UVM (49%), and ADAM6 in LUSC (45%)." (PMID 30107644, 2018). "Next, we analyzed 274 mutations in 24 cancer-relevant genes (Sequenom technology), including BRAF, NRAS, KIT c-MET, GNAS and GNAQ." (PMID 27057633, 2016).
cancer (continued). "Importantly, INPP5A was recently shown to be a highly specific vulnerability in UVM with activating mutations in GNAQ/GNA11, which occur in 90% of these cancers." (PMID 39995872, 2025). "In the current sample, the gene GNAQ was widely altered across cancer types." (PMID 34150649, 2021). "GNAS and GNAQ encode G-protein alpha subunit, and the viruses like cytomegalovirus and EBV have been identified to encode G proteins and their coupled receptors in their genomes to induce cancer initiation." (PMID 34926267, 2021). "GNAQ and GNA11 mutations are mutually exclusives and occur in about 2% of human cancers." (PMID 32532044, 2020). "Recent studies have shown that GNAQ is a pivotal cancer gene in blue naevi." (PMID 30517191, 2018). "Thus, there were few co-occurring mutations within the CYSLTR2 mutant cancers (between 5 and 19 coding mutations per sample), intuitively reducing the chance that the enrichment of semaphorin/plexin mutations in CYSLTR2 mutant UM relative to GNAQ/GNA11 mutant UM was a false discovery." (PMID 39013872, 2024). "These include known factors such as IDH1, as well as previously unreported genes, including four cancer driver genes (FGFR3, PPP6C, MAX, GNAQ)." (PMID 34944895, 2021). "For instance, in the current sample, the genes GNAS, GNAQ, and GNA11 were widely altered across cancer types, and these alterations often were accompanied by specific genomic abnormalities in AURKA, CBL, and LYN." (PMID 34150649, 2021). "Some proteins of the guanine nucleotide‐binding protein subunits GNAQ (Gqα), GNAS (Gs‐α), GNB1(Gβ1), and GNA13 (Gα) were overrepresented in the Circadian entrainment pathway as well as in cancer pathway." (PMID 31282103, 2019). "We hypothesized that, akin to PAK and RAC inhibitors, inhibitors of IMPDH would synergize with inhibitors of MEK in suppressing GNAQ- and GNA11-driven cancer cells." (PMID 41154654, 2025). "Mutant GNAQ and GNA11 may result in YAP activation and, as a consequence, can lead to cancer formation." (PMID 39518110, 2024). "Hence, while we show that mutant GNAQ regulates FASN expression in UM, there are other factors that can also regulate FASN in UM and other cancer types." (PMID 37444561, 2023). "GNAQ and ZFYVE28 may be involved in the plasticity and metabolic regulation of cancer cells." (PMID 41231350, 2025). "Interestingly, a new study based on clinical data and next-generation sequencing (NGS) on a cohort of 1348 patients with a wide range of cancers presented the most frequent coalterations in the presence of GNA alterations (GNAS, GNAQ, and GNA11) to be in AURKA, SRC, CBL and LYN genes." (PMID 32532044, 2020). "We show that CD47 is not modulated at different cancer stages, although patients with the lowest expression of CD47 show significant better progression-free survival, after correcting for the presence of BAP1, GNAQ, and GNA11 mutations." (PMID 31277366, 2019). "For example, the following top 100 MDS genes can be mentioned that are not yet covered by approved or experimental cancer or antineoplastic drugs [according to DrugBank, DGIdb, FDA6, HMDB, Tocris7, GeneCards databases]: GRB2, SOS1,SOS2, SHC1, GNB1, CREB1, GNG2, GNAQ, GNB5, GNAI2." (PMID 30728774, 2019).
adenocarcinoma (1 paper, 2013). A common cancer characterized by the presence of malignant glandular cells. "In the BNKL reconstructed network there is an indirect inhibition of MAPK7 by GNAQ which is stronger in the case of adenocarcinoma." (PMID 24565081, 2013).
vascular disorder (1 paper, 2016). A general term used to describe any disease affecting blood vessels]. "Postzygotic mosaicism for GNAQ mutations has been described as the major cause of SWS, a purely vascular disorder with no pigmentary phenotype." (PMID 26778290, 2016).
GNAQ also shares sentences with these, for which no sentence is quoted: heart failure (22 papers); breast carcinoma (13); cardiomyopathy (7); Obesity (7); colon carcinoma (6); Insulin resistance (6); neuroblastoma (6); Hypertension (5); Anxiety (4); glioblastoma (4); infection (4); mucosal (4); prostate carcinoma (4); /T cell lymphoma (3); angiosarcoma (3); Arthritis (3); asthma (3); Autoimmunity (3); cognitive deficits (3); dilated cardiomyopathy (3); epilepsy (3); gastric cancer (3); melanocytic neoplasm (3); metabolic disease (3); metastatic disease (3); retinal degeneration (3); schizophrenia (3); Stroke (3); systemic lupus erythematosus (3); type 2 diabetes (3).
A further 108 diseases each share a sentence with GNAQ in 3 papers or fewer.